RN7SL177P (RNA, 7SL, cytoplasmic 177, pseudogene)
Gene: Miscellaneous RNA gene on chromosome 5 (153,755,382 to 153,755,680, forward strand). Ensembl gene ENSG00000242976.
Homologues: Orthologues: chimpanzee Metazoa_SRP (98% identical), macaque Metazoa_SRP (93% identical). Paralogues in human: RN7SL1 (84% identical), RN7SL2 (83% identical), RN7SL3 (83% identical), RN7SL296P (81% identical), RN7SL660P (80% identical), RN7SL431P (80% identical), RN7SL451P (80% identical), RN7SL679P (80% identical), RN7SL732P (80% identical), RN7SL126P (80% identical), RN7SL322P (80% identical), RN7SL357P (80% identical), and 701 more.